PCSK9 (proprotein convertase subtilisin/kexin type 9)
Diseases named in the same sentence as PCSK9 in open-access papers (continued):
Sharing a sentence is not in itself a finding about the gene and the disease.
Sepsis (continued). "Here conducted a study on Chinese patients to identify the relationship between the circulating PCSK9 level and the 28-day mortality of sepsis." (PMID 37904138, 2023). "We have previously demonstrated that juvenile Pcsk9 null mice, challenged with sepsis, had a trend towards lower lipoprotein concentrations, higher bacterial burden in blood, and lower bacterial burden in the liver relative to the wildtype." (PMID 36778250, 2023). "A recent study discovered that inhibiting PCSK9 reversed the decline in eNOS expression brought on by sepsis; the results supported the author’s theory that sepsis-induced endothelium dysfunction enhanced PCSK9 expression." (PMID 37765005, 2023). "We have previously demonstrated that juvenile Pcsk9 null mice, challenged with sepsis, had a trend toward lower lipoprotein concentrations, higher bacterial burden in blood, and lower bacterial burden in the liver relative to the wildtype." (PMID 37365661, 2023). "Based on this knowledge, treatment with PCSK9 inhibitors can represent a new method of sepsis treatment." (PMID 37765005, 2023). "This study, for the first time, found that circulating PCSK9 has a high prognostic value in Chinese sepsis patients." (PMID 37904138, 2023). "PCSK9 levels in plasma appeared to be higher in septic shock and sepsis in comparison to SIRS (p = 0.139)." (PMID 37515197, 2023). "Evidence has also demonstrated that PCSK9 is closely related to inflammation, with a serum level increasing significantly during sepsis." (PMID 37904138, 2023). "Epidemiological data also confirm that levels of PCSK9 are elevated in patients with inflammatory diseases, particularly those with sepsis." (PMID 37904138, 2023). "According to a recent study, sepsis-related elevated PCSK9 expression triggered the TLR4/MyD88/NF-B and NLRP3 pathways to cause inflammation, leading to vascular endothelial dysfunction and lowered survival rates." (PMID 37765005, 2023). "PCSK9 concentrations are also elevated in patients with systemic inflammatory response syndrome and sepsis." (PMID 37765005, 2023). "Within the previous decade, proprotein convertase subtilisin/kexin type 9 (PCSK9) has been recognized to play a critical role in sepsis pathobiology." (PMID 37365661, 2023). "Juvenile Pcsk9 null and wildtype mice were subject to cecal slurry sepsis and endothelial markers were quantified." (PMID 36778250, 2023). "Our in vitro findings suggested the miR-15b-5p–SIRT4 axis as a suitable target for LPS-induced inflammatory pathways occurring in sepsis, and provide additional knowledge on the beneficial effect of i-PCSK9 in preventing vascular damage by targeting SIRT4." (PMID 37587410, 2023). "Lastly, we sought to corroborate the identified association between PCSK9 LOF genotype and endothelial markers in a juvenile murine model of sepsis." (PMID 37365661, 2023). "In the control cohort as well as the SIRS/sepsis cohort, men and women were found to have similar plasma PCSK9 levels (p = 0.732 and p = 0.337, respectively)." (PMID 37515197, 2023). "The current analysis showed that our 156 patients with systemic inflammatory response syndrome (SIRS) or sepsis had higher plasma PCSK9 levels in contrast with the 68 healthy controls." (PMID 37515197, 2023). "We sought to test the influence of PCSK9 LOF genotype on endothelial dysfunction in pediatric sepsis." (PMID 36778250, 2023). "Overall, these results demonstrate that i-PCSK9 protected endothelium in sepsis via SIRT4, indicating this epigenetic modulator as a possible innovative target against endothelial dysfunction induced by sepsis." (PMID 37587410, 2023). "After accounting for LDL and HDL concentrations, only Angpt-1 was significantly associated with PCSK9 LOF genotype in pediatric septic shock, with evidence for causal mediation on sepsis mortality." (PMID 36778250, 2023).
Sepsis (continued). "Our study showed that PCSK9 is upregulated in EC during in vitro sepsis condition, while its pharmacological inhibition reduces vascular inflammation and improves endothelial function." (PMID 37587410, 2023). "The current study shows that SIRS/sepsis patients have higher PCSK9 levels in comparison to healthy controls." (PMID 37515197, 2023). "Lastly, we sought to corroborate the association between PCSK9 LOF genotype and endothelial markers in a juvenile murine model of sepsis." (PMID 36778250, 2023). "Based on these data, ongoing clinical trials will test the efficacy of commercially available PCSK9 inhibitors as novel sepsis therapeutics (NCT03869073 and NCT03634293)." (PMID 37365661, 2023). "Recent studies have found that PCSK9 inhibitors have potential application value in the treatment of sepsis, some tumors, some viral infections, and other diseases." (PMID 36230934, 2022). "The bidirectional relationship between sepsis and lipoprotein metabolism is further underscored by the effect of sepsis on the levels of proprotein convertase subtilisin/kexin type 9 (PCSK9)." (PMID 36361756, 2022). "Proprotein convertase subtilisin/kexin type 9 (PCSK9) is a serine protease that is a mediator of the immune response to sepsis." (PMID 35770004, 2022). "Existing studies suggest that PCSK9 inhibitors have potential application value in the treatment of sepsis, some tumors, some viral infections, and other diseases." (PMID 36230934, 2022). "The indirect pro-inflammatory role of PCSK9 in infection make it an attractive target for modulation of the innate immune response in sepsis." (PMID 33920038, 2021). "Taking these data into account, it can be concluded that the use of drugs aimed at inhibiting the function of PCSK-9 should improve the prognosis of patients who develop sepsis as a result of infection." (PMID 33808697, 2021). "More importantly, this study also demonstrated the inhibitory effect of proprotein convertase subtilisin/kexin type 9 (PCSK9) on LPS scavenging and clearance in sepsis." (PMID 33939711, 2021). "In the future, studies are required to investigate the potential mechanisms and links, in order to promote the application of PCSK9 in the treatment of sepsis." (PMID 33123601, 2020). "PCSK9 levels have been reported to be elevated in the early phase of sepsis and to be correlated with complications." (PMID 31843964, 2020). "Proprotein convertase subtilisin/kexin type 9 (PCSK9) is often upregulated in the presence of sepsis and infectious diseases." (PMID 33123601, 2020). "Among first infection hospitalizations, we also did not observe significant associations between the presence of PCSK9 LOF variants and odds of sepsis." (PMID 30726226, 2019). "For example, in cecal ligation and puncture models of murine sepsis both Pcsk9 knockout and treatment of mice with PCSK9 antibody reduced measures of bacterial load." (PMID 31332258, 2019). "Some experimental studies have also suggested that PCSK9 deficiency confers protection against systemic bacterial dissemination and inflammation, while PCSK9 overexpression exacerbates multiorgan pathology and proinflammatory states in early sepsis." (PMID 31635200, 2019). "Our analysis conceptualized that the presence of a PCSK9 LOF variant would lead to decreased levels of PCSK9 protein, leading to decreased LDL-C and increased long-term rates of infection or sepsis." (PMID 30726226, 2019).
Sepsis (continued). "Surprisingly we observed discordant associations between PCSK9 and HMGCR genotypes with mortality of sepsis." (PMID 30736368, 2019). "We examined the association between presence of two genetic PCSK9 LOF variants and risk of infection and sepsis in community-dwelling adults." (PMID 30726226, 2019). "In fact, several reports have demonstrated a role of PCSK9 in inflammation, sepsis, immune function, and other aspects of lipoprotein metabolism." (PMID 31748600, 2019). "These fundamental differences in lipoprotein profiles between humans and mice also suggest that the choice of animal model should be carefully considered in future studies aiming to test PCSK9 inhibitors in vivo as a therapy for sepsis." (PMID 30002483, 2018). "In humans, plasma PCSK9 concentrations increased in a group of septic patients, which correlated with sepsis-induced cardiovascular or respiratory failure." (PMID 28600283, 2017). "These decreased levels upregulate PCSK9 transcription so that PCSK9 levels are increased during human sepsis." (PMID 27171436, 2016). "Nonetheless, genomics of sepsis studies have identified key pathways associated with specific organ dysfunctions and mortality, and have identified drug targets in sepsis (e.g., proprotein convertase subtilisin/kexin type 9 (PCSK9))." (PMID 27384443, 2016). "administration of PCSK9 inhibitors—to improve adverse outcomes due to inflammation triggered by pathogen toxins in patients with sepsis." (PMID 27171436, 2016). "Prior to establishing the sepsis model, we administered or did not administer ω-3 PUFAs or evolocumab to mice to mimic the levels of PUFAs and PCSK9 gene mutation in the pre-disease state of patients." (PMID 41608459, 2026). "Nonetheless, our study failed to provide evidence supporting the conclusion that PCSK9 inhibition can reduce the risk of sepsis." (PMID 40934270, 2025). "Targeting PCSK9 may represent a novel therapeutic strategy for preventing thrombotic complications in sepsis-induced lung injury." (PMID 41462858, 2025). "Targeting the PCSK9–platelet–NETs axis may offer a novel therapeutic approach for the prevention and treatment of sepsis-Induced lung Injury and thrombotic complications." (PMID 41462858, 2025). "A similar situation can be observed in sepsis + PCSK9 group." (PMID 41462858, 2025). "However, treatment with the PCSK9 inhibitor evolocumab led to a significant reduction in the expression of PCSK9 in the lung tissue of mice with sepsis." (PMID 41462858, 2025). "The same situation can also be detected in the sepsis + PCSK9 group." (PMID 41462858, 2025). "This condition was also observed in the sepsis + PCSK9 group of mice." (PMID 41462858, 2025). "We observed a significant increase in PCSK9 in the sepsis group compared to the control group." (PMID 41462858, 2025). "PCSK9 has been found to promote endothelial dysfunction during sepsis." (PMID 39982361, 2025). "In inflammation and sepsis, serum PCSK9 levels are elevated compared to those of healthy controls." (PMID 41233786, 2025). "In our study, PCSK9 was a significant predictor for hematological dysfunction occurring in sepsis." (PMID 38972879, 2024). "A recent meta-analysis of 20 randomized, double-blind, placebo-controlled trials concluded that treatment with PCSK9 blocking antibody did not increase the risk for sepsis, nor was this related to severe bacterial and viral infections." (PMID 39051245, 2024). "PCSK9 blockage in rodent models of sepsis reduced inflammation and improved survival." (PMID 39408818, 2024).
Sepsis (continued). "Importantly, PCSK-9 inhibition reverses impaired VE-cadherin expression observed in in vitro and in vivo models of sepsis." (PMID 38521954, 2024). "PCSK9 represents an innate immune system response to sepsis." (PMID 38972879, 2024). "In patients with sepsis, SARS-CoV-2 infection caused an increase in plasma PCSK9 levels in contrast to sepsis patients lacking a viral infection." (PMID 39408818, 2024). "Additionally, elevated serum PCSK9 levels have been found in individuals with systemic inflammatory response syndromes and sepsis." (PMID 39055658, 2024). "On the other hand, PCSK9 loss-of-function variants did not protect from sepsis upon bacterial infection, and PCSK9 blockage did not lower the risk of severe infections and sepsis." (PMID 39408818, 2024). "Moreover, LDL-C and PCSK9 were significantly higher in the severe sepsis group when compared to the sepsis group, as p = 0.04 and ≤ 0.001, respectively." (PMID 38972879, 2024). "It is plausible that such variation may have a more significant effect on organ homeostasis and sepsis survival than serum PCSK9 concentrations during sepsis." (PMID 36778250, 2023). "Patients with liver cirrhosis have an increased risk for sepsis-related death, but a causal effect of PCSK9 on survival has not been described." (PMID 37515197, 2023). "Given the potential pleiotropic effects of PCSK9 on the endothelium, beyond canonical effects on serum lipoproteins, both of which may influence sepsis outcomes, we sought to test the influence of PCSK9 LOF genotype on endothelial dysfunction." (PMID 37365661, 2023). "Improved vascular endothelial function in sepsis may be achieved through the clinical therapeutic target of PCSK9 inhibition." (PMID 37765005, 2023). "In accordance with this study, a meta-analysis including 20 studies and 64,984 patients showed that treatment with PCSK9-inhibiting antibodies did not modify the risk for severe viral and bacterial infections and sepsis." (PMID 37515197, 2023). "Several lines of evidence have suggested that anti-PCSK9 therapy could positively affect sepsis and septic shock." (PMID 37466835, 2023). "The 28-day mortality of sepsis increased significantly as the baseline circulating PCSK9 level exceeded 370 ng/ml, indicating circulating PCSK9 levels may be a potential biomarker to predict the prognosis of sepsis." (PMID 37904138, 2023). "Therefore, given that an interesting relationship also exists between i-PCSK9 and endothelial function, we examined its ability in LPS-induced EC inflammation, thus contributing to the design of new approaches for sepsis treatment." (PMID 37587410, 2023). "Nowadays, genetic and clinical trials have explored whether circulating PCSK9 is a prognosis biomarker of sepsis." (PMID 37904138, 2023). "Accordingly, PCSK9 LOF or pharmacological inhibition during sepsis may lead to the significant reduction in these dysfunctional lipids with consequent beneficial effects on endothelial dysfunction." (PMID 37365661, 2023).
Sepsis (continued). "In a mouse model, PCSK9 overexpression aggravated LPS-induced sepsis, while knockout alleviated it." (PMID 37904138, 2023). "This study showed that plasma PCSK9 is induced in SIRS/sepsis patients in contrast to the controls." (PMID 37515197, 2023). "Similarly, in a mouse model for sepsis, administration of PCSK9 inhibitor diminished inflammation and increased survival, while PCSK9 overexpression had the opposite effect." (PMID 35162992, 2022). "A recent study suggested that neither genetic variants in PCSK9 nor predicted PCSK9 expression were associated with sepsis, cardiovascular events or death." (PMID 35770004, 2022). "In addition, in a sepsis-mouse model, transgenic mice overexpressing PCSK9 showed increased levels of thrombin-antithrombin complexes and decreased levels of protein C, suggesting an important role for PCSK9 in the sepsis-induced hypercoagulable state." (PMID 35323669, 2022). "This hypothesis is indirectly supported by findings on proprotein convertase subtilisin/kexin type 9 (PCSK9), which was also found to be increased in sepsis." (PMID 36551906, 2022). "Another previous study also showed that PCSK9 over-expression could increase plasma IL-6 concentration, while knockout of PCSK9 could decrease plasma IL-6 levels and attenuate organ inflammatory response in the mouse septicemia model." (PMID 35252378, 2022). "In addition, PCSK9 inhibitors have been used to improve the treatment of sepsis and some malignant tumors." (PMID 36230934, 2022). "The rationale behind this observation is unclear, and they suggest that children should be excluded from sepsis clinical trials involving PCSK9 inhibitors until the unknown effect of PCSK9 dysfunction in young children is clarified." (PMID 36230934, 2022). "Interestingly, in our model we also have identified other novel markers, such as endoglin and PCSK9, whose pathophysiological role in sepsis deserves further investigation." (PMID 36119052, 2022). "PCSK9 loss-of-function mutations were not linked to a lower risk for infection and sepsis among 10,924 participants enrolled in the REasons for Geographic and Racial Differences in Stroke (REGARDS) cohort." (PMID 35162992, 2022). "In addition to cardiovascular diseases, PCSK9 is also used in pancreatic cancer, sepsis, and Parkinson’s disease." (PMID 36230934, 2022). "Furthermore, PCSK9 is involved in glucose metabolism, renal function, immune responses, inflammation, and sepsis." (PMID 34681838, 2021). "Actually, complete PCSK9 knockout seems to be protective in sepsis." (PMID 34070931, 2021). "In the experimental sepsis model, PCSK-9 gene overexpressing transgenic mice subjected to cecal ligation and puncture were characterized by a much greater increase in IL-6, thrombin–antithrombin (TAT), and the incidence of kidney and liver damage compared to the control group." (PMID 33808697, 2021). "Moreover, in a similar model of sepsis carried out in mice with decreased expression of the gene for PCSK-9, a decrease in the concentration of myeloperoxidase and IL-10 and a reduction in the frequency of lung and liver damage were characteristic." (PMID 33808697, 2021). "Our review provided an additional insight in the role of PCSK9 in sepsis, which might serve as a potential target for the treatment of sepsis." (PMID 33123601, 2020). "Thus, it has been suggested that the propagated increase of PCSK9 plasma concentrations in sepsis is a secondary effect following hypocholesterolemia after an inflammatory stimulus." (PMID 31843964, 2020). "Unfortunately, little is known about the roles of PCSK9 in inflammation and sepsis." (PMID 33123601, 2020).